IL1B (interleukin 1 beta)
Diseases named in the same sentence as IL1B in open-access papers (continued):
Sharing a sentence is not in itself a finding about the gene and the disease.
malaria (continued). "Interleukin (IL)-1β is a proinflammatory cytokine that has a role in disease-related inflammation, including malaria." (PMID 36309676, 2022). "The meta-analysis confirmed that patients with severe malaria had higher IL-1β levels than those with uncomplicated malaria." (PMID 36309676, 2022). "We found that the method for IL-1β quantification was a confounder in the meta-analysis, and the results showed higher IL-1β levels in uncomplicated malaria than healthy controls in studies using both the bead-based assay and ELISA for IL-1β quantification." (PMID 36309676, 2022). "Studies have reported an increase in IL-1β in patients with severe malaria, notably cerebral malaria." (PMID 36309676, 2022). "Based on the limitations of the number of studies included in the meta-analysis and high levels of heterogeneity, further studies are needed to conclude that differences in IL-1β levels can be useful for monitoring the malaria severity." (PMID 36309676, 2022). "Meta-analysis results confirmed that patients with uncomplicated malaria had comparable IL-1β levels to healthy controls." (PMID 36309676, 2022). "The meta-analysis results showed that severe malaria had a higher mean of IL-1β levels than uncomplicated malaria (P < 0.01, pooled MD: 1.92 pg/mL, 95% CI: 0.60–3.25 pg/mL, I2: 90.41%, 6 studies)." (PMID 36309676, 2022). "This study aimed at determining the impact of intestinal helminths on malaria parasitaemia, anaemia and pyrexia considering the levels of IL-1β among outpatients in Bamenda." (PMID 33651792, 2021). "In this work, the authors also suggest an important role for IL-1β (rs1143634) and IL-18 (rs5744256) SNPs in shaping malaria clinical outcomes." (PMID 33672278, 2021). "Intestinal helminths exacerbated the clinical outcomes of malaria in the patients and increased levels of IL-1β were observed in co-infected patients with anaemia, pyrexia and higher parasitaemia." (PMID 33651792, 2021). "The response of γδ T cells to stimulation in vitro with malaria antigens is characterised by proliferation as well as production of cytokines including IFN-γ, IL-1β, and TNF-α which have been associated with protection against malaria disease." (PMID 34666102, 2021). "While redundant, our data indicate that in these malaria models the mechanism by which caspases-1/11 promotes IL-1β release involves GSDM-D, whereas caspase-8 seems to mediate expression of pro-IL-1β and TNFα." (PMID 32929083, 2020). "In our earlier studies, we found that MO-DCs are an important source of active caspase-1, IL-1β and have a pathogenic role in ECM and acute respiratory distress syndrome in malaria (MA-ARDS) models." (PMID 32929083, 2020). "While peripheral levels of TNF-α, IL-1β and IL-6 were similar in women with Malaria and CHB, the pro-inflammatory cytokines were significantly increased in those with Malaria+CHB, which further suggests a possible additive effect of the infections." (PMID 31002731, 2019). "Nod-Like Receptor (NLR) P3/P12 dependent activation of caspase-1 is likely to be a key event in mediating systemic production of IL-1β with hypersensitivity to secondary bacterial infection during malaria." (PMID 31771607, 2019). "We propose that elevated levels of IL‐1β induced by ROS contribute to the systemic inflammation in malaria." (PMID 31265218, 2019). "IL-1β expression was unchanged throughout uncomplicated malaria condition but got upregulated drastically among severe cases by 1.19-fold compared to EC control." (PMID 31614626, 2019). "There was an associated increase in IL1-β (P = 0.03), IL-6 (P = 0.001), CXCL1 (P = 0.001) and MCP-1 (P = 0.003) serum levels in malaria-infected mice, when compared to the control group, on GD18.5." (PMID 31391498, 2019). "The response of γδ T cells to stimulation in vitro with malaria antigens is characterised by proliferation as well as production of cytokines including IFN-γ, IL-1β, and TNF-α which have been associated with both malaria protection and pathology." (PMID 31600250, 2019).
malaria (continued). "Mechanistically, we show that AIM2 and NLRP3 inflammasome activation by YM infection produces IL-1β in pDCs and potentially many other cell types, depending upon exposure of malaria." (PMID 30470758, 2018). "For example, higher concentrations of GM-CSF and eotaxin following TLR7/8 stimulation, of IL-1β following TLR9 stimulation, and of IL-7 following IL-3 stimulation, were associated with an increased hazard of malaria in the first year of life." (PMID 30454004, 2018). "The release of free hemozoin, presumably from parasites that turn over during the replicative process, coincides with the induction of proinflammatory cytokines, including IL-1β and TNFα, and the periodic fevers characteristic of malaria." (PMID 29495555, 2018). "Cytokines such as IL-1β have been shown to inhibit mTOR activity and similar cytokine profiles have been reported in malaria-infected pregnant women." (PMID 28049467, 2017). "Both malaria and dengue have been associated with a strong activation of acute phase response (IL-6, TNF-α, and IL1-β) and Th1 cytokines (IFN-γ and IL-12)." (PMID 27128316, 2016). "So far, several studies show that severe malaria is associated with increased TNF-α, IFN-γ, and IL-1β but decreased IL-10 and TGF-β." (PMID 26602091, 2015). "IFN-γ and TNF showed the highest relative number of network interactions in the severe malaria group and IL-1β and IL-6 showed the highest relative number of interactions in the hyperbilirubinaemia group." (PMID 26466783, 2015). "We conclude that NLRP12/NLRP3-dependent activation of caspase-1 is likely to be a key event in mediating systemic production of IL-1β and hypersensitivity to secondary bacterial infection during malaria." (PMID 24453977, 2014). "We propose that inflammasome and IL-1β are important components of the proinflammatory priming and the exquisite sensitivity to superinfection during malaria." (PMID 24453977, 2014). "In lethal P. chabaudi malaria, there occurs biphasic, two-wavy increase in serum IL-1β, TNFα, and IL-6 with the first wave peaking on day 1 p.i. and the second wave peaking at maximal parasitemia on day 8 p.i.." (PMID 25408684, 2014). "Course and outcome of both human and experimental blood-stage malaria critically depend on a finely tuned balance between both pro-inflammatory cytokines, as, e.g., IL-1β, TNFα, IFNγ, IL-6, and IL-12, and anti-inflammatory cytokines such as IL-4 and IL-10." (PMID 25408684, 2014). "In this study we dissected the mechanisms of induction and the importance of the pyrogenic cytokine, IL-1β in the pathogenesis of malaria." (PMID 24453977, 2014). "Our results demonstrate the critical role of the innate immune receptors named Toll-Like Receptors and inflammasome on induction, processing and release of active form of IL-1β during malaria." (PMID 24453977, 2014). "We next studied caspase-1 activation and IL-1β release in peripheral blood mononuclear cells (PBMCs) from patients undergoing febrile malaria." (PMID 24453977, 2014). "Overall, our data argue that the IFN-γ, TNF-α and MyD88 role on hypersensitivity to septic shock during malaria is, at least in part, mediated by inflammasome-dependent release of IL-1β." (PMID 24453977, 2014). "Another consequence of the decreased ROS generation during malaria would be the uncontrolled activation of caspase-1 and release copious amounts of active IL-1β by phagocytes, as previously reported in patients with chronic granulomatous disease (CGD)." (PMID 24453977, 2014). "Before the malaria season, children's immune cells responded to iRBCs by producing pro-inflammatory mediators such as IL-1β, IL-6 and IL-8." (PMID 24743880, 2014). "The observation that children had higher levels of TNF and IL-1β in acute phase compared to life-long malaria-exposed adults also suggests a different ability to regulate pro-inflammatory and anti-inflammatory responses according to age and/or exposure." (PMID 23437061, 2013).
malaria (continued). "IL-8 and IL-1β were higher only in immigrants with malaria (52.45 [30.33; 100.25] pg/mL and 2.1 [2.1; 3.7] pg/mL, respectively) compared to immigrants with other diseases (37.86 [14.81; 48.08] pg/mL, P=0.0218 and 2.1 [2.1; 2.1] pg/mL, P=0.0377, respectively)." (PMID 23967342, 2013). "Immigrants and travelers with malaria had higher levels of IFN-γ, IL-6, and IL-10 (P<0.0100) than patients with other diseases, and IL-8 and IL-1β were elevated in immigrants with malaria (P<0.0500)." (PMID 23967342, 2013). "Only five uncomplicated malaria patients had detectable serum IL-1β levels, and they were all heterozygous for Δ22 and had medium length GT repeat alleles." (PMID 22336003, 2012). "The IL1B -5839C and IL4R 1902A alleles are 8.2% and 6.2% respectively more frequent in malaria patients than in controls." (PMID 23217179, 2012). "In the children examined in this study, cerebral malaria patients had elevated serum levels of IFN-γ, IL-1β, and IL-10 compared to uncomplicated malaria patients." (PMID 22336003, 2012). "After population structure correction, only IL1B -5839C > T and IL4R 1902A > G polymorphisms were associated with malaria susceptibility." (PMID 23217179, 2012). "All donors showed a response towards IL-1β production, drawing special attention for its possible protective role in early innate immune responses to malaria." (PMID 20470442, 2010). "It has been reported that increased concentrations of TNF and IL1β in serum are observed in severe malaria patients." (PMID 19840389, 2009). "This suggests that another MyD88 dependent receptor such as IL-1R is involved and supports a role for IL-1β in malaria-related pathology." (PMID 19696895, 2009). "Hz is released into the blood circulation during the rupture of red blood cells, which coincides with the production of many cytokines such as interleukin-1β (IL-1β), responsible in part for the periodic fever that is characteristic of the malaria disease." (PMID 19696895, 2009). "In this study, IL1B -31C>T, IL1B 3953C>T, and IL1RA VNTR polymorphisms were analysed in Thai malaria patients to examine the possible association of these polymorphisms with cerebral malaria." (PMID 16098232, 2005). "IL-1β and IL-1RA levels are higher in the serum of cerebral malaria patients than in patients with mild malaria." (PMID 16098232, 2005). "Estimated haplotype frequencies of IL1B -31C>T and IL1RA VNTR polymorphisms in Thai malaria patients." (PMID 16098232, 2005). "In this study, possible association of IL1B -31C>T and IL1RA VNTR polymorphisms with cerebral malaria was assessed in 316 Thai malaria patients." (PMID 16098232, 2005). "Notably, cytokine levels were elevated in patients with malaria and typhoid comorbidity, particularly IL-1β, IL-2, TNF-α, and IFN-γ." (PMID 40014608, 2025). "However, sustained high-level production of IL-1β can induce anemia, a phenomenon also documented in numerous other disease models beyond malaria." (PMID 40980010, 2025). "This could also explain why the IL-1β level in this present study was highest in typho-malaria group with a lower IL-10 level." (PMID 40014608, 2025). "Additionally, higher levels of IL-1β and tumor necrosis factor (TNF) -α have been linked to malaria severity, underscoring their importance in the inflammatory response." (PMID 41194029, 2025). "Their mechanism of action involves NLRP3 inflammasome activation, dendritic cell recruitment, and cytokine production (IFN-γ, IL-1β) and can be particularly valuable for adjuvant vaccines to diseases requiring strong cellular immunity (e.g., malaria, tuberculosis, HIV)." (PMID 40870989, 2025). "An increased serum concentration of IL-1β in the presence of chloroquine and malaria could neutralize the immunosuppressive microenvironment of the solid Ehrlich tumor." (PMID 38774541, 2024).
malaria (continued). "High concentrations of immunocomplexes containing parasite DNA induce the AIM2 and NLRP3 inflammasome assembly, caspase-1 activation and IL-1β secretion in monocytes from infected patients, thereby stimulating systemic inflammation during acute malaria episodes." (PMID 39548522, 2024). "Moreover, the mechanical antinociception, the thermal hyperalgesia, and the antiedema effect observed in mice treated with chloroquine and healed from malaria can be related to the increase in the serum level of IL-1β." (PMID 38774541, 2024). "Thus, the role of monocytes, and in particular the activation of the NLRP3 inflammasome and Il-1β generation, in P. falciparum infection and pathogenesis of malaria is still debatable." (PMID 37141324, 2023). "An analysis of the cord blood revealed that TNF, IL-1β, and IL-5 were associated with severe malaria but IL-4, IL-6, IFN-γ, and IL-10 did not relate to severe malaria." (PMID 36668942, 2023). "As TNF-α and IL-1β could support splenic erythropoiesis in the inflammatory setting, they might also play a role in malaria-induced splenic erythropoiesis at the early stage of P. yoelii infection." (PMID 37180169, 2023). "Moreover, 6 studies provided quantitative data on IL-1β levels in severe (555 cases) and uncomplicated malaria (1059 cases) and were included in the meta-analysis." (PMID 36309676, 2022). "Therefore, new investigation for malaria therapeutics should consider IL-1β and IL-33 as potential targets." (PMID 36362246, 2022). "Finally, most of the included studies (16/20, 80%) used microscopy alone for to identify the malaria parasites and bead-based assay (13/20, 65%) for IL-1β quantification." (PMID 36309676, 2022). "However, the overall meta-analysis result confirmed higher IL-1β levels than those in uncomplicated malaria." (PMID 36309676, 2022). "The sensitivity analysis using the leave-one-out method showed robust meta-analysis results, demonstrating a higher mean of IL-1β levels in severe malaria than uncomplicated malaria (P < 0.05 when each study was removed and the meta-analysis was rerun, 6 studies)." (PMID 36309676, 2022). "Therefore, meta-analyses to assess differences in IL-1β levels between various types of malaria, including between patients with severe malaria, patients with uncomplicated malaria and healthy controls were performed." (PMID 36309676, 2022). "Therefore, meta-analyses to compare differences in IL-1β levels between patients with severe malaria, patients with uncomplicated malaria and healthy controls were performed." (PMID 36309676, 2022). "In the literature, inconsistent reports exist on the influence of IL-1β on malaria severity." (PMID 36309676, 2022). "Fourth, the meta-analysis results revealing a higher mean of IL-1β levels in severe malaria compared with uncomplicated malaria had more certainty than those demonstrating a difference in mean IL-1β levels between patients with uncomplicated malaria and healthy controls." (PMID 36309676, 2022). "A search of PubMed, Scopus, EMBASE and reference lists was conducted for articles providing data on IL-1β levels between patients with severe malaria, patients with uncomplicated malaria and healthy controls between January 1988 and March 2022, using a combination of search terms." (PMID 36309676, 2022). "Malaria patients co-infected with each species of intestinal helminths recorded higher IL-1β levels (IL-1β > 121.68 ± 58.86 pg/mL) and the overall mean (139.63 ± 38.33pg/mL) was higher compared with levels in malaria (121.68 ± 58.86 pg/mL) and helminth (61.78 ± 31.69pg/mL) infected patients alone." (PMID 33651792, 2021). "Genetic variants in IL-1β (rs1143634) and FcγRIIA/CD32 (rs1801274)—both in allelic, dominant and co-dominant models—were significantly associated with protection from both P. falciparum infection and clinical malaria." (PMID 33593344, 2021).
malaria (continued). "However, excessive production of pro-inflammatory cytokines such IL-1β, IL-6 and TNF by monocytes/macrophages can result in systemic inflammation that causes fever and other disease manifestations of malaria." (PMID 33822828, 2021). "Similar RNA profiles were obtained for both the CHMI subjects and symptomatic, malaria-experienced adults, with increases in IFNγ, TNFα, IL-1β, as well as the related nuclear factor kappa-light-chain-enhancer of activated B cells (NFκB) signaling and regulatory cascades." (PMID 31900030, 2020). "process caspase-8, indicating their potential role in IL-1β release and pathogenesis of malaria." (PMID 32929083, 2020). "Altogether, we provide evidence that P. vivax and P. falciparum infection leads to induction and activation of caspases-4 and -8 as well as GSDM-D in monocytes, which may contribute to the overall amount of IL-1β and pathogenesis of malaria." (PMID 32929083, 2020). "In addition, Il1b expression in the liver was upregulated in the malaria-infected group, when compared to controls (P < 0.05)." (PMID 31391498, 2019). "In the context of malaria, altered placental cytokine concentrations have been demonstrated in the presence of infection, with increased expression of both pro-inflammatory cytokine (IL-1β and TNF) and chemokines (CXCL8), and decreased expression of IL-6." (PMID 31188820, 2019). "Besides, TNF-α and IL-1β levels were also found elevated during SM, similar to previous findings, which reflect the role of malaria pigment or hemozoin in the disease outcome." (PMID 31614626, 2019). "Although inflammatory responses, including interferon gamma (IFN-γ), IL-12, IL-1β, IL-2, and TNF-α, play important roles that facilitate parasite clearance, circulating high levels of these cytokines have been associated with malaria immunopathology." (PMID 28399920, 2017). "Quantification of levels of pro-inflammatory cytokines, including TNF-α, IFN-γ, IL-1β, IL-2, IL-8, IL-6, IL-12, and GM-CSF in children with malaria in the three transmission areas revealed a pattern of decreasing cytokine levels with increasing transmission intensity (Accra > Navrongo > Kintampo)." (PMID 28399920, 2017). "However, a recent study reported an elevated neutrophil count that correlated with expression levels of the pro-inflammatory mediators IL-1β and IL-8 in human severe malaria." (PMID 27168977, 2016). "The inverse association between parasitemia and elevated levels of IL-1β, IL-1Ra, IL-12, IL-15, IL-17, IFN-γ, and IFN-α in G[−] coinfected children, compared to malaria monoinfection, suggests that this profile may favor induction of antiparasitic activities." (PMID 27418744, 2016). "Furthermore, TNF-α, a critical cytokine in malaria pathogenesis was shown to mediate expression of inflammasome components and pro-IL-1β." (PMID 24453977, 2014). "Furthermore, we found that the malaria-primed monocytic cells produce deleterious amounts of IL-1β when exposed to a second microbial challenge, being an important component of the overwhelming inflammatory response observed during bacterial superinfection." (PMID 24453977, 2014). "Similarly to murine malaria, extremely high levels of IL-1β are produced by PBMCs from P. vivax or P. falciparum malaria patients exposed to bacterial components." (PMID 24453977, 2014). "Support for this modulatory hypothesis comes from the description that IL-10 and IL-4 can directly down regulate pro-inflammatory cytokines such as IL-6, TNF and IL-1β and prevent severe forms of malaria." (PMID 23433077, 2013). "The IL1B gene -5839C > T and IL4R 1902A > G polymorphisms and IL12RB1 -1094A/-641C and TNF -1031 T/-863A/-857 T/-308 G/-238 G haplotypes were associated with malaria susceptibility after population structure correction (p = 0.04, p = 0.02, p = 0.01 and p = 0.01, respectively)." (PMID 23217179, 2012).